SMAD4 (SMAD family member 4)
Diseases named in the same sentence as SMAD4 in open-access papers (continued):
Sharing a sentence is not in itself a finding about the gene and the disease.
gastric cancer (continued). "Recent findings showed that, RUNX3 and Smad4, which function as tumor-suppressor genes, are associated with gastric cancer." (PMID 26134263, 2015). "SMAD4 upregulated level associated prolong overall survival in gastric cancer patients." (PMID 37670969, 2023). "In addition, low Smad4 expression was associated with invasion, metastasis and tumour-node-metastasis stages in our series of gastric cancer patients." (PMID 27685626, 2016). "With regard to a mechanism of SMAD4 nuclear loss, various mechanisms including dysregulation of nucleocytoplasmic shuttling, loss of heterozygosity, promoter hypermethylation and proteasome degradation are found in gastric carcinomas." (PMID 27438138, 2016). "In gastric cancer, loss of Smad4 staining was found to be significantly associated with the rate of lymph node metastasis (OR = 2.11, 95% CI: 1.03–4.34; Pheterogeneity = 0.038) but not with tumor histology (OR = 0.87, 95% CI: 0.45–1.69; Pheterogeneity = 0.037)." (PMID 25333693, 2014). "In addition, Smad4 has been shown to inhibit the expression of β-catenin, which is implicated in gastric cancer progression." (PMID 22710759, 2012). "Indeed, a recent study has also shown that genes located adjacent to EGFR at 7p11 or SMAD4 at 18q21 were in close association with one another and may play a role in the pathogenesis of advanced gastric carcinoma." (PMID 22559327, 2012). "Upregulation of miR187 in gastric cancer significantly downregulated the protein expression of Smad4, TGF-β1, and NER components (ERCC3 and ERCC4), which boosted the cisplatin sensitivity." (PMID 40303493, 2025). "In gastric cancer cells, miR-146a overexpression improved cell proliferation and inhibited apoptosis, as well as downregulated SMAD4 gene expression." (PMID 40277937, 2025). "SMAD4 has been reported as one of the downstream targets of miR-146a-5p in gastric cancer, glioma, and prostate cancer." (PMID 40338154, 2025). "Circ_SMAD4 promotes gastric cancer tumorigenesis by recruiting TCF4 to facilitate CTNNB1 transcription in the nucleus and sequestering miR-1276 in the cytoplasm to prevent the silencing of CTNNB1 mRNA, thereby activating the Wnt/β-catenin pathway." (PMID 40708910, 2025). "Inhibition of the TGF-β/SMAD4 signaling pathway resulted in suppressed proliferation and migration of gastric cancer cells, concomitant with a diminished glycolytic capacity." (PMID 38686046, 2024). "Despite the known role of SMAD4 in regulating the onset of glycolytic processes in these tumors, its role in gastric cancer has been underexplored." (PMID 38686046, 2024). "EBV-miRNA-BART6-5p exhibits pronounced upregulation in EBV-associated gastric cancer tissues and EBV-positive cells, while its target gene SMAD4 demonstrates downregulated expression." (PMID 38686046, 2024). "In vitro, its silencing inhibited cancer cell migration and invasion and reduced phospho-Smad2 and phospho-Smad4 levels, while its ectopic expression promoted gastric cancer progression and counteracted TGF-β inhibitors." (PMID 39768197, 2024). "Extracolonic involvement, massive gastric polyposis and a more aggressive phenotype have been associated with SMAD4 + JPS, predisposing to gastric cancer." (PMID 38066625, 2023). "The high expression of SMAD1, SMAD2, and SMAD4 in gastric cancer tissues is significantly correlated with the prognosis of patients." (PMID 36969909, 2023). "In the literature, a gene-phenotype association has been reported relating to gastric polyposis and gastric cancer being more common in SMAD4 DCV carriers than BMPR1a DCV carriers." (PMID 37400896, 2023).
gastric cancer (continued). "Current knowledge of genotype–phenotype correlations between SMAD4 variants and JPS is that individuals are more inclined to have upper gastrointestinal (UGI) polyposis and higher gastric cancer risk, as compared to BMPR1A." (PMID 38066625, 2023). "For example, the low TOB1 expression activates gastric cancer progression by inhibiting Smad4- and activating β‐catenin-mediated signaling pathways." (PMID 38062199, 2023). "Some Wnt pathway-related circRNAs (circ0005654, circ-SFMBT2, circ_SMAD4, circRNA_0044516, and circHIPK3) are markedly upregulated in gastric cancer." (PMID 35513849, 2022). "For example, miR-324-3p accelerates the development of gastric cancer through Smad4-mediated Wnt/β-catenin signaling,miR-324-3p restrains the invasion and migration in nasopharyngeal carcinoma via directly targeting WNT2B." (PMID 34980214, 2022). "For example, miR‐98 can promote IVDD through the IL‐6/STAT3 signalling pathway, whereas miRNA‐558 promotes gastric cancer progression by attenuating Smad4‐mediated repression of heparinase expression." (PMID 35187741, 2022). "Western blot was utilized to detect TSPAN12, TGF-β1, and SMAD4 expression in gastric cancer tissues and normal tissues." (PMID 35879950, 2022). "In other words, Smad4/ADAR1/hsa_circ_0004872/miR-224/Smad4 axis regulated tumor size and local lymph node metastasis in gastric cancer." (PMID 35898396, 2022). "Circular RNA hsa_circ_0004872, dramatically downregulated in gastric cancer, molecular sponges miR-224 to upregulate the expression of the miR-224 downstream targets p21 and Smad4 by targeting the 3′-UTR." (PMID 35898396, 2022). "The knockdown of circ_SMAD4 blocked gastric cancer progression by negatively regulating cell growth." (PMID 35513849, 2022). "As shown in this study, it was observed the decrease in the expression of TGF-β1 and SMAD4 proteins in gastric cancer tissues." (PMID 35879950, 2022). "Collectively, these results demonstrate that the high expression level of three members of SMADs (SMAD1, SMAD2, and SMAD4) is significantly correlated with favorable OS of gastric cancer patients, which is opposite to SMAD3." (PMID 34138687, 2021). "The results showed that the high expression of three members of SMADs (SMAD1, SMAD2, SMAD4) was correlated with afavorable OS of gastric cancer patients." (PMID 34138687, 2021). "Inhibition of Smad4 enhanced cell proliferation, viability, and migration, which leads to the development of gastric cancer." (PMID 34959833, 2021). "EZH2, NFE2L2, REST, SMAD4 and SUZ12 were all implicated as common transcriptional regulators of DEGs in glioma, sarcoma, breast and stomach cancers, suggesting that altered AMPK signaling converged on similar groups of transcriptional targets." (PMID 32807122, 2020). "Smad4 has been reported to suppress gastric cancer and be involved in modulating cell proliferation, apoptosis, and migration." (PMID 29103082, 2018). "While antral stem cells expressing Lgr5, Mist1 or Sox2 may be among the gastric cancer origin cells in the setting of Apc loss, Lgr5+ cells have been implicated in more invasive types of gastric cancer, characterized by the simultaneous loss of Pten and Smad4, or by the loss of Lats1 and Lats2." (PMID 30384487, 2018). "Meanwhile, knockdown or over-expression of HPSE prevented the gastric cancer cells from alteration in the growth, invasion and angiogenesis induced by ectopic expression of miR-558 or Smad4, respectively." (PMID 27685626, 2016).
gastric cancer (continued). "Lower Smad4 expression was observed in gastric cancer tissues with deeper gastric wall invasion (P<0.001), lymph node metastasis (P<0.001), distant metastasis (P=0.029) or advanced tumour-node-metastasis stage (P<0.001)." (PMID 27685626, 2016). "The present study suggests that BARF1 suppressed SMAD4 through NFκB-dependent miR-146a upregulation in stomach cancer cells." (PMID 27438138, 2016). "In 90 fresh gastric cancer specimens, lower Smad4 levels or higher HPSE expression were observed than those in normal gastric mucosa, similar to results from Gene Expression Omnibus datasets." (PMID 27685626, 2016). "Treatment of endothelial cells with the medium preconditioned by Smad4 over-expressing gastric cancer cells reduced their tube formation capability." (PMID 27685626, 2016). "In clinical gastric cancer specimens, up-regulation of miR-558 and down-regulation of Smad4 were positively correlated with HPSE expression." (PMID 27685626, 2016). "In matrigel invasion assay, stable over-expression of Smad4 inhibited the invasion capacity of gastric cancer cells." (PMID 27685626, 2016). "Stable over-expression of miR-558 attenuated the enrichment of Smad4 on HPSE promoter induced by ectopic expression of Smad4 in gastric cancer cells." (PMID 27685626, 2016). "Ectopic expression or knockdown experiments indicated that miR-558 promoted the in vitro and in vivo tumorigenesis and aggressiveness of gastric cancer cell lines via attenuating Smad4-mediated repression of HPSE expression." (PMID 27685626, 2016). "We focused on RUNX3 and Smad4 since it has been previously shown that RUNX3 and Smad4 as tumor suppressor genes are associated with gastric cancer." (PMID 26134263, 2015). "LOH on chromosome 18q21 is found in 30–71 % of gastric cancers, and DPC4 (Smad4)/DCC have been postulated to be the major targets." (PMID 26207151, 2015). "In gastric cancer, patients with Smad4-nagative expression had high rates of lymph node involvement." (PMID 25333693, 2014). "The expression of Smad4 has been known to be reduced in gastric cancer, and re-expression of Smad4 has been reported to inhibit tumor progression." (PMID 22710759, 2012). "Collectively, our study demonstrates that the overexpression of Tob1 inhibits gastric cancer progression by activating Smad4- and inhibiting β-catenin-mediated signaling pathways." (PMID 22710759, 2012). "Low Smad4 expression, detected by immunohistochemistry, and poorer five-year survival was shown in 249 patients with advanced gastric cancer and in 258 esophageal squamous cell carcinomas (P <0.05)." (PMID 20462450, 2010). "The 18q region is also known to harbor two well-known gastric cancer associated tumor suppressor genes DCC (18q21.3) and SMAD4 (18q21.1)." (PMID 20187983, 2010). "Additionally, we observed that EBV-miRNA-BART6-5p regulates the target gene SMAD4, influencing the glycolysis process in gastric cancer cells." (PMID 38686046, 2024). "Thus, we identified that BART6-5p modulates the TGF-β/SMAD4 signaling pathway to promote glycolysis in gastric cancer cells." (PMID 38686046, 2024). "In Blatter and colleagues’ study, 7/127 SMAD4 carriers had gastric cancer, and 0/94 in BMPR1A." (PMID 38066625, 2023). "If polyps are detected, UGI endoscopy would be repeated annually with appropriate resection, though complete or partial gastrectomy may be warranted in cases of massive gastric polyposis, dysplasia and gastric cancer, as seen in SMAD4 + JPS patients." (PMID 38066625, 2023). "It was shown that SMAD4 deletion allowed gastric cancer cells to evade tumour immunity." (PMID 37685308, 2023). "This provided potential evidence that downregulated TGF-β1 and SMAD4 might participate in gastric cancer progression." (PMID 35879950, 2022). "Taken together, FKB could increase proapoptotic proteins and decrease antiapoptotic proteins in gastric cancer cells, which was related to SMAD4." (PMID 35879950, 2022).
gastric cancer (continued). "Abnormal TGF-β/SMAD4 pathway contributes to tumorigenesis of gastric cancer." (PMID 35879950, 2022). "Our data showed that after transfection with si-SMAD4, the therapeutic effect of FKB was significantly weakened, indicating that FKB may inhibit gastric cancer partly through the TGF-β1/SMAD4 pathway." (PMID 35879950, 2022). "Finally, we verified that TGFB1I1, TGFBR1, SMAD9 and SMAD4 are low expressed in gastric cancer by immunohistochemistry at the protein level, and RCAN2 is also low expressed in gastric cancer." (PMID 36483555, 2022). "Smad4 has been reported to be a tumor suppressor in gastric cancer, and studies on experimental gastric cancer revealed that Smad4 could be downregulated to promote cell proliferation and block apoptosis." (PMID 34959833, 2021). "Whether Smad4 could regulate the Wnt/beta-catenin signaling pathway in gastric cancer still remains unknown." (PMID 29103082, 2018). "Moreover, ChIP and real-time qPCR revealed the enrichment of Smad4 around its binding site in gastric cancer cells." (PMID 27685626, 2016). "We demonstrated that Smad4 inhibited the growth, invasion, metastasis and angiogenesis of gastric cancer cells, and patients with low expression of Smad4 have lower survival probability, indicating the tumour suppressive functions of Smad4 during the progression of gastric cancer." (PMID 27685626, 2016). "Moreover, down-regulation of miR-558 rescued the gastric cancer cells from Smad4 knockdown-altered biological features." (PMID 27685626, 2016). "In stomach cancer tissues, miR-146a was expressed at higher levels, and more frequent NFκB nuclear positivity immunohistochemically, but not of SMAD4 nuclear loss was found in the EBV-positive group compared with the EBV-negative group." (PMID 27438138, 2016). "SMAD4 nuclear loss, as detected by immunohistochemical staining in stomach cancer tissues, tended to be associated with poor survival rates in EBV-positive stomach cancer patients." (PMID 27438138, 2016). "In addition, we demonstrated that miR-558 promoted the HPSE expression via attenuating the binding and repressive effects of Smad4 on HPSE promoter in gastric cancer cells." (PMID 27685626, 2016). "The findings that ectopic expression of miR-558 was able to rescue the gastric cancer cell lines from Smad4-inhibited biological behaviours indicate that the oncogenic functions of miR-558 are exerted, at least in part, through repressing the Smad4 activity in gastric cancer." (PMID 27685626, 2016). "In conclusion, the present study demonstrates that Tob1 functions as a tumor suppressor protein in gastric cancer cells, at least in part, by inducing apoptosis and inhibiting proliferation, migration and invasion via the activation of Smad4- and suppression of β-catenin-mediated signaling pathways." (PMID 22710759, 2012). "Furthermore, low expression of TGF-β1 and SMAD4 was found in gastric cancer tissues." (PMID 35879950, 2022). "In addition, SMAD4 functions as a tumor suppressor gene in stomach cancer." (PMID 27438138, 2016). "Furthermore, miR-558 is up-regulated in gastric cancer, and promotes the transcription of HPSE via abolishing the binding of Smad4 to its promoter, resulting in increased in vitro and in vivo growth, invasion, metastasis and angiogenesis of gastric cancer cells." (PMID 27685626, 2016). "The subsequent evaluation aimed to observe their impact on gastric cancer cell proliferation, migration, and glycolytic processes, with the TGF-β/SMAD4 signaling pathway value clarified using a TGF-β inhibitor." (PMID 38686046, 2024).
gastric cancer (continued). "To elucidate the impact of EBV-miR-BART6-5p on gastric cancer cells, we explored its regulatory mechanisms within the TGF-β/SMAD4 pathway." (PMID 38686046, 2024). "In our study, we, for the first time, report that SMAD4, the target gene corresponding to EBV-miR-BART6-5p, influences tumorigenesis through glycolysis in gastric cancer." (PMID 38686046, 2024). "Zheng et al37 showed that endogenous miR‐558 decreased the binding of Smad4 to HPSE, activated the transcription and expression of HPSE, and promoted tumorigenesis and invasion of gastric cancer cells both in vitro and in vivo." (PMID 37563869, 2023). "In a subgroup analysis based on tumour node metastasis (TNM) stage, SMAD4 and SMAD7 showed the most significant prognostic differences in patients with stage I gastric cancer." (PMID 37685308, 2023). "In this study, we extracted the protein from gastric cancer tissues and found that the protein expression of TGF-β1, SMAD4, and TSPAN12 was prominently decreased in gastric cancer." (PMID 35879950, 2022). "Moreover, molecularly targeted therapies against PI3K and the TGF-β axis may be candidates for treatment of advanced GSC, although therapeutic strategies for targeting mutations in PTEN and SMAD4 have not been established for gastric cancer." (PMID 33603111, 2021). "BARF1 mediates positive regulation of miR-146a in NF-κB dependent manner to repress SMAD4, an TSG in stomach cancer, promoting cell proliferation and progression in GC." (PMID 33072180, 2020). "Moreover, SMAD4 loss may be useful as a negative prognostic factor in EBV-positive stomach cancer patients." (PMID 27438138, 2016). "Lower Smad4 and higher HPSE levels were noted in gastric cancer cell lines, when comparing with primary stomach epithelial cells." (PMID 27685626, 2016). "In conclusion, we have shown that Smad4 is under-expressed and suppresses the transcription of HPSE through directly binding to its promoter in gastric cancer." (PMID 27685626, 2016). "In addition, consistent with the tumor-suppressive role of SMAD4, the SMAD4 gene locus showed homozygous deletions in those human clinical TCGA cancer samples and its mRNA expression was highly down-regulated in TCGA stomach cancer samples, indicating its deletion." (PMID 26694352, 2015). "For example, the expression of SMAD4 was lower, and that of SMAD7 was significantly higher, in the gastric cancer tissues than in the peri-tumoral tissues." (PMID 25295107, 2014). "Since METTL3 is known to regulate TGF-β signaling in lung and gastric cancers, and SMAD4 is a critical mediator of TGF-β signaling, we checked the expression levels of a few downstream effectors of SMAD4-dependent TGF-β signaling in METTL3-depleted SCC-25 cells, by western blot analysis." (PMID 40338154, 2025). "The transcription factor Smad family member 4 (SMAD4), a core factor in the TGF-β signaling pathway, increases the transcriptional activity of FZD4 and activates the Wnt pathway; FZD10 promotes the proliferation of gastric cancer cells." (PMID 38952556, 2024). "In this study, we found that EBV-miRNA-BART6-5p can target SMAD4, effectively increasing glycolysis in gastric cancer cells by regulating the TGF-β/SMAD4 signaling pathway, thereby enhancing the proliferation and metastasis of gastric cancer cells." (PMID 38686046, 2024). "Subsequently, we investigated whether SMAD4 is regulated by EBV miRNA-BART6-5p, thereby influencing the cell phenotype and glycolytic processes of gastric cancer cells." (PMID 38686046, 2024).